TMSB10 (thymosin beta 10)
Diseases named in the same sentence as TMSB10 in open-access papers (continued):
Sharing a sentence is not in itself a finding about the gene and the disease.
colorectal cancer (4 papers, 2020 to 2024). A primary or metastatic malignant neoplasm that affects the colon or rectum. "For instance, declined TMSB10 expression was involved in the DNMT1/miR-152-3p/TMSB10 axis to suppress the colorectal cancer development." (PMID 38035023, 2023). "Furthermore, DNMT1 maintained the methylation of miR-152-3p to regulate TMSB10 expression, thereby affecting the biological characteristics of colorectal cancer cells." (PMID 36276278, 2022). "This study was to investigate that how DNMT1 affected the biological characteristics of colorectal cancer (CRC) cells via modulating methylation of microRNA (miR)‐152‐3p and thymosin β 10 (TMSB10) expression." (PMID 32918845, 2020).
glioblastoma (4 papers, 2022 to 2025). The most malignant astrocytic tumor (WHO grade IV). "According to the signature that included four genes (TMOD2, CACNG2, PLOD3, and TMSB10), glioblastoma patients were divided into high and low risk score groups." (PMID 35788194, 2022). "In glioblastoma, a study constructed a signature by four m7G-related genes (TMOD2, CACNG2, PLOD3, and TMSB10) and could predict the prognosis of glioblastoma patients." (PMID 36732869, 2023). "Although the role of TMSB10 in glioblastoma has not been studied, existing publications have shown that TMSB10, as a cancer-promoting gene, can promote cell invasion and cancer progression." (PMID 35788194, 2022).
glioma (4 papers, 2021 to 2023). A benign or malignant brain and spinal cord tumor that arises from glial cells (astrocytes, oligodendrocytes, ependymal cells). "Further studies are needed to elucidate the underlying mechanisms linking TMSB10 expression, age, and glioma pathogenesis." (PMID 38026448, 2023). "Further investigation is needed to explore the underlying molecular mechanisms through which TMSB10 promotes glioma progression, such as its impact on cell migration, invasion, and angiogenesis." (PMID 38026448, 2023). "Given the growing interest in immunotherapy targeting glioma, we investigated the associations between TMSB10 expression and immune cell infiltration within the tumor microenvironment." (PMID 38026448, 2023). "Future studies should aim to elucidate the molecular mechanisms underlying TMSB10-mediated oncogenic effects, including its interaction with other key molecules and pathways in glioma development and progression." (PMID 38026448, 2023). "The correlation between TMSB10 expression and molecular characteristics such as IDH status and 1p/19q codeletion highlights the potential molecular subtypes in glioma associated with TMSB10 dysregulation." (PMID 38026448, 2023). "Survival analysis indicated that high TMSB10 expression was significantly associated with worse overall survival, disease-specific survival, and progression-free survival in glioma patients." (PMID 38026448, 2023). "TMSB10 expression, glioma grade, age, and IDH mutation status were significantly associated with OS." (PMID 36163046, 2022). "Strikingly, we found that TMSB10 was specifically overexpressed in glioma tissues and was closely associated with glioma prognosis, biological function, and immune regulation." (PMID 36163046, 2022). "Furthermore, we explored the associations between TMSB10 expression and critical prognostic factors in glioma, namely, IDH status and 1p/19q codeletion." (PMID 38026448, 2023). "The association between TMSB10 expression and wild-type IDH suggests that TMSB10 may be involved in the molecular pathways associated with aggressive glioma subtypes." (PMID 38026448, 2023). "Moreover, we found a significant association between TMSB10 expression and age, with glioma patients over the age of 60 displaying a higher proportion of high TMSB10 expression compared to those aged 60 or below." (PMID 38026448, 2023). "Collectively, our findings highlight TMSB10 as a promising therapeutic target and prognostic biomarker in glioma, opening avenues for further research into the underlying mechanisms and potential clinical applications of targeting TMSB10 in this devastating disease." (PMID 38026448, 2023). "Moreover, high TMSB10 expression was associated with high macrophage infiltration and immunotherapy resistance in gliomas." (PMID 36163046, 2022). "The positive correlation between TMSB10 expression and advanced histological grades indicates its involvement in glioma aggressiveness and malignant transformation." (PMID 38026448, 2023). "While our study provides valuable insights into the oncogenic role of TMSB10 in glioma, there are several limitations that should be acknowledged." (PMID 38026448, 2023). "In our study, we observed a positive correlation between TMSB10 expression and age, with higher TMSB10 levels in glioma patients over the age of 60." (PMID 38026448, 2023). "To validate the clinical findings and further investigate the functional implications of TMSB10 in glioma, we conducted in vitro and in vivo experiments." (PMID 38026448, 2023). "Glioma cells with TMSB10 knockdown and control cells were subcutaneously injected into the flanks of nude mice." (PMID 38026448, 2023). "Functional experiments supported the oncogenic function of TMSB10 in glioma cell proliferation and tumor growth." (PMID 38026448, 2023). "We aim to elucidate the expression pattern of TMSB10 in glioma tissues compared to normal brain tissues and evaluate its clinical relevance in patient outcomes." (PMID 38026448, 2023).
glioma (continued). "In this study, we investigated the oncogenic role of TMSB10 in glioma and its potential as a prognostic biomarker." (PMID 38026448, 2023). "Next, we compared the TMSB10 expression level among different grade, and we found glioma patients with advanced grade had higher TMSB10 expression (P=1.3e-36)." (PMID 37275863, 2023). "In our study, we investigated the correlations between TMSB10 expression and immune cell infiltration within the glioma microenvironment." (PMID 38026448, 2023). "The upregulation of TMSB10 in glioma tissues compared to normal brain tissues provides valuable insights into its involvement in glioma pathogenesis." (PMID 38026448, 2023). "In this study, we aimed to elucidate the oncogenic role of thymosin beta-10 (TMSB10) in glioma through comprehensive analyses of patient data from the TCGA and GTEx databases." (PMID 38026448, 2023). "For bioinformatics analyses, previous study only presented the pan-cancer expression pattern and biological and immunomodulatory function of TMSB10, and most of results focus on glioma." (PMID 37275863, 2023). "Our analysis revealed significant correlations between TMSB10 expression and specific immune cell subsets in glioma." (PMID 38026448, 2023). "In the in vitro experiments, we utilized the U251 and LN229 glioma cell lines to evaluate the effect of TMSB10 knockdown on cellular growth rates." (PMID 38026448, 2023). "The physiological functions of TMSB10 in the brain are not fully understood, but its upregulation in glioma suggests its potential contribution to tumor development and progression." (PMID 38026448, 2023). "To validate our findings, we performed the experiments in vitro and found low expression of TMSB10 inhibited clonogenic formation ability, invasion, and migration in glioma cells." (PMID 37275863, 2023). "TMSB10 knockdown led to reduced glioma cell proliferation in vitro, indicating its role in promoting tumor growth." (PMID 38026448, 2023). "In vitro, low expression of TMSB10 inhibited clonogenic formation ability, invasion, and migration in glioma cells." (PMID 37275863, 2023). "Functionally, knockdown of TMSB10 in glioma cells resulted in reduced cellular growth rates and impaired tumor growth in xenograft models." (PMID 38026448, 2023). "Our findings revealed a significant upregulation of TMSB10 expression in glioma tissues compared to normal brain tissues, with higher expression levels observed in tumors of advanced histological grades." (PMID 38026448, 2023). "Survival analysis revealed that high TMSB10 expression was significantly correlated to worse clinical outcomes in glioma patients." (PMID 38026448, 2023). "TMSB10 expression was upregulated in glioma tissues and correlated with advanced histological grades, age, wild-type IDH status, and noncodeletion of 1p/19q." (PMID 38026448, 2023). "In this study, we found that TMSB10 was significantly higher in glioma tissues compared to normal brain tissues according to the data from TCGA and GTEx databases." (PMID 38026448, 2023). "To further investigate the biological function of TMSB10 in glioma, we performed gene set variation analysis (GSVA) to identify cancer hallmarks that are closely associated with TMSB10 expression." (PMID 36163046, 2022). "The role of TMSB10 in the malignant progression of glioma, the promotion of macrophage infiltration,and immunosuppressive polarization, and the combination drug efficacy were assessed via biological function assays." (PMID 36163046, 2022). "Considering that the prognosis of glioma patients is influenced by various factors, we performed univariate Cox regression analysis to further evaluate the prognostic value of TMSB10 in glioma patients in the CGGA, TCGA and Gravendeel datasets." (PMID 36163046, 2022). "In conclusion, these results suggested that TMSB10 promotes cell proliferation, migration and invasion, playing oncogenic roles in glioma." (PMID 36163046, 2022).
glioma (continued). "To further demonstrate the pro-carcinogenic function of TMSB10 in glioma, we performed several related experiments in vitro and in vivo." (PMID 36163046, 2022). "Further pan-cancer analysis showed that TMSB10 is closely related to the biological function, immune regulation and prognosis of glioma." (PMID 36163046, 2022). "Taken together, our findings suggest that TMSB10 affects the regulatory network of glioma at multiple levels, providing a comprehensive overview of how TMSB10 affects glioma pathogenesis." (PMID 36163046, 2022). "Further integration with other biological experiments also revealed the key roles of TMSB10 in the MES transformation of glioma, the promotion of macrophage infiltration and immunosuppressive polarization." (PMID 36163046, 2022). "Our results suggested that TMSB10 promotes cell proliferation, migration and invasion, thereby playing oncogenic roles in glioma." (PMID 36163046, 2022). "GSEA also showed that these functional gene set signatures were enriched in TMSB10-high glioma samples." (PMID 36163046, 2022). "ROC analysis for TMSB10 expression and glioma grade showed that the AUC was 0.929, suggesting that TMSB10 has the potential to serve as a biomarker for predicting glioma grade." (PMID 36163046, 2022). "Pearson correlation analysis also showed that TMSB10 was positively correlated with immune checkpoints, macrophage-related immunosuppressive molecules and stromal-related genes in six public glioma datasets and the Qilu dataset." (PMID 36163046, 2022). "Further integration with other biological experiments revealed the key roles of TMSB10 in glioma proliferation, invasion, and mesenchymal transformation." (PMID 36163046, 2022). "Further integration with other biological experiments revealed the key roles of TMSB10 in the malignant progression of glioma, the promotion of macrophage infiltration and immunosuppressive polarization." (PMID 36163046, 2022). "To validate the function of TMSB10 in glioma proliferation, metastasis and invasion, we performed several related experiments in vitro and in vivo." (PMID 36163046, 2022). "Our results also showed that the PTEN mutation rate and PI3K-AKT pathway activity were upregulated in TMSB10-high glioma samples." (PMID 36163046, 2022). "We also characterized the multiomics molecular features of TMSB10 in glioma, identifying various novel dysregulated pathways." (PMID 36163046, 2022). "The primary objective of this study is to explore the oncogenic function of TMSB10 in glioma." (PMID 38026448, 2023). "TMSB10 may play a role in the age-related changes within the tumor microenvironment, potentially promoting glioma progression in older patients." (PMID 38026448, 2023). "In addition, we examined the correlations between TMSB10 expression and several important clinical characteristics in glioma patients." (PMID 38026448, 2023). "Age-related changes in the tumor microenvironment and immune system may contribute to the increased TMSB10 expression observed in older glioma patients." (PMID 38026448, 2023). "Furthermore, recognizing the growing importance of the tumor microenvironment and immunotherapy in glioma treatment, we aim to explore the correlations between TMSB10 expression and immune cell infiltration." (PMID 38026448, 2023). "We further explored the function role of TMSB10 in glioma through cell experiments." (PMID 37275863, 2023). "This suggests that TMSB10 expression may serve as a valuable prognostic biomarker in glioma, aiding in patient stratification and treatment decision-making." (PMID 38026448, 2023). "We next evaluated the prognostic effect of TMSB10 in gliomas via Kaplan–Meier survival analyses." (PMID 38026448, 2023). "Additionally, we seek to comprehensively understand the functional implications of TMSB10 in glioma through a combination of in vitro and in vivo experiments." (PMID 38026448, 2023).
glioma (continued). "Understanding the intricate crosstalk between TMSB10 and the immune system in glioma could provide insights into its potential as a therapeutic target for immunotherapy approaches." (PMID 38026448, 2023). "Our study provides compelling evidence for the oncogenic role of TMSB10 in glioma." (PMID 38026448, 2023). "TMSB10 may involve glioma immune regulation progression by promoting PD-L1 expression levels via activating STAT3 signaling pathway." (PMID 37275863, 2023). "The exact molecular pathways and signaling networks involving TMSB10 in glioma remain largely unknown." (PMID 38026448, 2023). "Furthermore, the impaired tumor growth observed in xenograft models with TMSB10-knockdown cells suggests that TMSB10 contributes to glioma progression in vivo." (PMID 38026448, 2023). "Furthermore, IHC analysis of our local glioma clinical samples validated that TMSB10 expression was highest in GBM samples, consistent with the results of the database analyses." (PMID 36163046, 2022). "In addition, TMSB10 expression showed a significant positive correlation with immune checkpoint expression in glioma patients." (PMID 36163046, 2022). "Consequently, we performed multivariate Cox regression analysis and found that the expression level of TMSB10 was an independent prognostic factor for glioma patients in the CGGA, TCGA and Gravendeel cohorts." (PMID 36163046, 2022). "In addition, TMSB10 was also positively correlated with the expression of most immunomodulatory molecules in these three glioma datasets." (PMID 36163046, 2022). "TMSB10 was closely related to the biological function, immune regulation and prognosis of glioma." (PMID 36163046, 2022). "Flow cytometric analysis showed that TMSB10 knockdown could induce apoptosis.and G1/S arrest in glioma cells." (PMID 36163046, 2022). "Similarly, the association between TMSB10 expression and noncodeletion of 1p/19q further supports its potential role in distinct molecular subtypes of glioma." (PMID 38026448, 2023). "Furthermore, TMSB10 may involve glioma immune regulation progression by promoting PD-L1 expression levels via activating STAT3 signaling pathway." (PMID 37275863, 2023). "However, the specific role of TMSB10 in glioma remains largely unexplored." (PMID 38026448, 2023). "Furthermore, TMSB10 may involve glioma immune regulation progression by promoting PD-L1 expression levels via activating STAT3 signaling pathway in glioma cells." (PMID 37275863, 2023). "The pathways enrichment analysis indicated TMSB10 was positively associated with IL6/JAK/STAT3 signaling pathway, and we also found TMSB10 was positively associated with IL-6 in patients with primary/recurrent glioma (grade III: r=0.46, P<0.001, grade IV: r=0.317, P=0.003)." (PMID 37275863, 2023). "The interplay between TMSB10 expression and immune cell infiltration highlights the complex interactions within the tumor microenvironment and may have implications for immunotherapeutic approaches targeting glioma." (PMID 38026448, 2023). "We also identified multiple drugs targeting cells with high TMSB10 expression and validated that knockdown of TMSB10 improved the efficacy of selumetinib (a MEK1/2 inhibitor approved by the FDA for the treatment of neurofibromatosis-associated tumors) and anti-PD1 treatment in glioma." (PMID 36163046, 2022). "We also identified multiple drugs targeting high TMSB10 expression and validated that knockdown of TMSB10 improved the efficacy of selumetinib (a MEK1/2 inhibitor approved by the FDA for the treatment of neurofibromatosis-associated tumors) and anti-PD1 treatment in glioma." (PMID 36163046, 2022). "Previous study explored the TMSB10 promoted glioma progression via YAP1/AKT/ERK1/2, but we explored the TMSB10 promoted glioma progression via IL6/JAK/STAT3 signaling pathway." (PMID 37275863, 2023). "We observed a significant correlation between TMSB10 expression and WHO grade, a key histopathological characteristic in glioma." (PMID 38026448, 2023).
glioma (continued). "In our cohort, TMSB10 positively correlated with glioma grade, and the results showed that the GBM samples had the highest TMSB10 expression." (PMID 36163046, 2022). "The results showed that carcinogenic processes such as inflammatory responses, stromal activation, cell proliferation and invasion-related pathways were positively correlated with TMSB10 expression in both LGG and GBM in these three glioma datasets." (PMID 36163046, 2022). "Our findings revealed higher TMSB10 expression in glioma patients with wild-type IDH and noncodeletion of 1p/19q." (PMID 38026448, 2023). "Overall, these results revealed that TMSB10 could be a potential biomarker for alterations in TME cell infiltration and carcinogenic pathways in glioma." (PMID 36163046, 2022). "Additionally, the immunohistochemical results for our local glioma tissues further validated that TMSB10 expression levels were higher in glioma tissues than in normal tissues and were upregulated with increasing grade." (PMID 36163046, 2022). "The top 20 co-expressed neighbors were selected, and the core genes PFN1, CALR, thymosin beta 10 (TMSB10), HLA.A, CD74 (HLADG), HLA.DRA, HLA.B, TUBB, and TUBA1A were found to play pivotal roles in the network, suggesting that immune genes are involved in glioma formation." (PMID 34660294, 2021).
lung carcinoma (4 papers, 2018 to 2024). "However, the clinicopathological significance of TAMs-associated TMSB10 in lung cancer remains largely unknown." (PMID 33349268, 2020).
ovarian carcinoma (4 papers, 2017 to 2022). A malignant neoplasm originating from the surface ovarian epithelium. "However, the expression of TMSB10 has also been shown to be downregualted in ovarian cancer tissues and cells and overexpression of TMSB10 diminishes tumor growth and proliferation." (PMID 28179017, 2017).
pancreatic cancer (4 papers, 2010 to 2022). "For pancreatic cancer, the tag GGGGAAATCG, belonged to the thymosin beta-10 (TMSB10) gene, is reported to upregulate in human pancreatic carcinoma, but not in control pancreatic tissue." (PMID 21179408, 2010).
liver cancer (3 papers, 2019 to 2024). An epithelial or non-epithelial malignant neoplasm that arises from the liver. "We also examined the top most informative features and observed that the most informative nullomers were found at liver cancer-associated genes, including FTH1, EEF2, TMSB10, ACTB and the long non-coding RNA MALAT among others." (PMID 38351138, 2024).